APOE (apolipoprotein E)
Diseases named in the same sentence as APOE in open-access papers (continued):
Sharing a sentence is not in itself a finding about the gene and the disease.
malaria (17 papers, 2008 to 2025). Malaria is a serious and sometimes fatal disease caused by a parasite that commonly infects a certain type of mosquito which feeds on humans. "Until today, only two field studies have investigated the association between APOE alleles with malaria outcomes." (PMID 24116184, 2013). "parasite densities were two to three times greater in children with the APOE Ɛ4 allele, which would increase the risk of both anemia and symptomatic malaria with parasite densities rising above the fever threshold." (PMID 24116184, 2013). "In our study, we demonstrated that specifically the APOE Ɛ4 allele was associated with higher median malaria parasite densities in West African children likely due to the importance of cholesterol availability to parasite growth and replication." (PMID 24116184, 2013). "ApoE is involved in the pathogenesis and susceptibility to other infectious diseases, including herpes simplex virus-1, hepatitis C virus, hepatitis E virus, varicella zoster virus, Epstein–Barr virus, malaria, L. monocytogenes (LM), and K. pneumoniae." (PMID 39660133, 2024). "Previous studies have reported that there may be a close association between APOE gene polymorphism and infection with malaria." (PMID 25574218, 2015). "Given a fitness cost to higher parasite densities, our data are consistent with the proposal that malaria may have selected against the APOE Ɛ4 allele." (PMID 24116184, 2013). "Given that cholesterol is an important nutrient for malaria parasites, we examined whether APOE Ɛ4 was a risk factor for Plasmodium infection, in terms of prevalence or parasite density." (PMID 24116184, 2013). "The data presented here that indicates a selective interaction between PFE1590w and ApoE alleles ε3 and ε4 is consistent with the notion that this interaction might be related to malaria pathogenesis." (PMID 18937849, 2008). "This means that individuals carrying APOE ɛ3 and ɛ4 alleles are more likely to develop severe malaria (cerebral malaria and severe anemia); therefore, the higher APOE ɛ2 allele frequency in the Fang population on Bioko Island may be the result of selection due to malaria." (PMID 25574218, 2015). "In addition, we observed an epistatic interaction between APOE and HbS genes in relation to regulation of malaria parasite density indicating a potential linked pathway of regulation of parasite density, possibly by modulating expression of the P. falciparum major variant surface antigen." (PMID 24116184, 2013). "In addition, Gambian children homozygous for the ApoE ε2 allele are more likely to suffer early malaria infection, while heterozygotes carrying the ApoE ε3 and ε4 alleles are more likely to suffer severe malaria, including cerebral malaria and severe anaemia." (PMID 18937849, 2008). "ApoE is a physiological regulator of lipid homeostasis with the capacity to modulate the immune response against pathogens, such as malaria, mycobacteria, and viruses." (PMID 40231469, 2025). "This study examined ApoE variants and CVD risk assessment in malaria and HIV patients attending a tertiary health facility in Cape Coast, Ghana, to understand how ApoE variation influences CVD risk in this cohort." (PMID 37134097, 2023). "ε3/ε3 was the most distributed ApoE genotype accounting for 51.55% of the total participants whiles ε2/ε2 was found in 2.48% of participants, with 1 in malaria-only and 3 in HIV-only patients." (PMID 37134097, 2023). "This is in line with previous reports showing that blood proteins such as apolipoprotein E, serum amyloid A, LPS binding protein, complement factor H, albumin, and fibrinogen that were found to be elevated in malaria individuals are able to bind to HZ." (PMID 31905972, 2019). "Using a proteomic approach, we previously identified unique biomarkers in the sera of malaria-infected individuals, including apolipoprotein E (ApoE)." (PMID 27647324, 2016).
malaria (continued). "Our results suggest that Superoxide dismutase, Vitronectin, Titin, Apolipoprotein E, Serum amyloid A, and Haptoglobin are potential predictive markers for malaria severity." (PMID 27090372, 2016). "This is paralleled by APOE, where APOE4 alleles are protective against some infectious diseases (e.g., malaria) but increase the proliferation of other pathogens (e.g., HSV-1, HIV) (see earlier)." (PMID 24656052, 2014). "The asexual malaria parasite MOI median (value, Inter Quartile Range [IQR]) and MOI>1 prevalence (n/N (%)) in relation to the APOE alleles for children only positive for P. falciparum (excludes P. malariae, and mixed P. falciparum/P. malariae) (N=206)." (PMID 24116184, 2013). "In summary, we have identified APOE Ɛ4 as a significant host genetic modifier of malaria parasite density in West African children." (PMID 24116184, 2013). "The asexual malaria parasite prevalence (n (%)) and median density (value/μL, Inter Quartile Range [IQR]) in relation to the APOE alleles for children only positive for P. falciparum (excludes P. malariae, and mixed P. falciparum/P. malariae) (N=234)." (PMID 24116184, 2013). "Some specific examples of malaria biomarkers bound to HZ included LPS binding protein (P18426), apolipoprotein E (P02649), hemoglobin subunit alpha (P69905), serum amyloid A (P02735) and complement factor H (A5PL14)." (PMID 22028888, 2011). "This study examined ApoE variation and CVD risk assessment in malaria and HIV patients." (PMID 37134097, 2023). "Both malaria and HIV potentially cause lipid dysregulation, and the variable distribution of ApoE alleles and genotypes among different populations may predispose individuals to CVD risk." (PMID 37134097, 2023). "However, in consideration of the safety records of Art in treating malaria in the past 2 decade and its effectiveness in AS rats herein and ApoE-/- mice reported previously, we propose Art to be a promising agent for AS treatment." (PMID 36817159, 2023). "However, APOE ε4 seems to be protective against infectious diseases such as hepatitis C virus and malaria." (PMID 26574747, 2015). "This study was not designed to investigate the effect of APOE Ɛ4 polymorphisms on malaria morbidity outcomes." (PMID 24116184, 2013). "There are several potential interactions between APOE Ɛ4 and malaria." (PMID 24116184, 2013). "The asexual malaria parasite prevalence (n (%)) and median density (value/μL, Inter Quartile Range [IQR]) in relation to the APOE alleles for children positive for Plasmodium spp. (includes P. falciparum, P. malariae, and mixed P. falciparum/P. malariae) (N=257)." (PMID 24116184, 2013). "Conversely, up-regulation of apolipoprotein E was observed in the malaria patients." (PMID 22912677, 2012). "The level of Apolipoprotein E (Apo E) also markedly increased in malaria patients." (PMID 22028888, 2011). "Whether ApoE plays a critical role to tame malaria-related inflammatory responses or to detoxify the system from HZ, is still to be investigated." (PMID 22028888, 2011). "The peptides of LBP, apolipoprotein E, serum amyloid A, alpha-1-antitrypsin and hemoglobin subunit alpha were found to be significantly higher in samples from malaria patients." (PMID 22028888, 2011). "Malaria sporozoites depend on low-density lipoprotein (LDL) receptor-related protein (LRP) and on cell surface HSPGs for host cell invasion through chondroitin sulfate A (CSA) binding to LRP at the same site that apolipoprotein E (apo E) and Lf bind." (PMID 36015327, 2022). "We have established that ApoE is essential for the development of ECM and that the absence of this protein protects mice from malaria-associated neuropathology." (PMID 27647324, 2016). "Up to 75% of the circulating RBCs were observed to be infected with the malaria parasite in the non-symptomatic ApoE−/− mice by the end of the infection." (PMID 27647324, 2016).
Nephropathy (17 papers, 2005 to 2024). A nonspecific term referring to disease or damage of the kidneys. "In this report, we show that a deficiency in TRAIL in ApoE-/- mice resulted in a heightened inflammatory state in the kidney, as well as exacerbated nephropathy." (PMID 24667560, 2014). "Several studies focused on the effects of ApoE after cardiopulmonary bypass and reported a higher incidence of inflammation and nephropathy in patients with the E4 allele; depending on the trial more or less neurological sequelae were seen with the E2 allele." (PMID 19691831, 2009). "ApoE is a glycoprotein crucial for lipid metabolism, with polymorphism in its gene potentially influencing the susceptibility to metabolic disorders and their subsequent complications, such as diabetic foot ulcers and nephropathy." (PMID 38066772, 2023). "It is possible that the nephropathy in T2DM may be associated with the polymorphism of the APOE gene." (PMID 27781209, 2016). "The enrichment of lipid metabolism genes, including APOE, further emphasizes the role of lipid regulation in DFU progression, with recent findings linking APOE alleles to abnormal lipid metabolism and kidney damage." (PMID 39409014, 2024). "In our ApoE KO mice with adenine-induced nephropathy, FGF23 was increased, and Vdr and Cyp27b1 mRNA levels were down-regulated in the kidney, providing evidence for impaired bone growth conditions." (PMID 36009040, 2022). "There was a 40% and 60% reduction in the mRNA level of Vdr (p < 0.05) and Cyp24a1 (p < 0.01) in ApoE KO mice with adenine-induced nephropathy." (PMID 36009040, 2022). "Quantification of atherosclerotic lesions in the aortic root surprisingly identified ApoE KO mice with adenine-induced nephropathy as being protected." (PMID 36009040, 2022). "The content of hepatic cholesterol, cholesteryl ester, and triglycerides of ApoE KO mice with adenine-induced nephropathy remained unchanged when compared to those with normal renal function." (PMID 36009040, 2022). "TRAIL-/-ApoE-/- mice had significantly increased urine protein, urine protein:creatinine ratio, plasma phosphorous, and plasma cystatin C, with accelerated nephropathy." (PMID 24667560, 2014). "Nephropathy was induced by adenine in Apolipoprotein E knockout mice." (PMID 36009040, 2022). "Consistent with more severe nephropathy, TRAIL-/-ApoE-/- mice had reduced appetite and were eating less than ApoE-/- mice within the last 4 w of the study; supported by the markedly reduced plasma glucose levels at 20 w, even though TRAIL-deficient mice were still insulin resistant." (PMID 24667560, 2014). "Our study shows that adenine-induced nephropathy could be achieved in ApoE KO mice fed with an atherogenic diet without severe weight loss." (PMID 36009040, 2022).
proteinopathy (17 papers, 2019 to 2026). "APOE*4 allele is considered the highest-risk allele with adverse effects on lipid metabolism, cardiovascular diseases, and different proteinopathies, including AD, FTD, LBD, and ALS, while APOE*2 is considered a protective allele." (PMID 38002991, 2023). "The differential APOE allelic effect on AD risk is likely regulated in large part due to its impact on AD-related proteinopathies." (PMID 34935119, 2022). "• Consider genetic manipulation to model particular aspects of human TBI, such as humanized tau or TDP-43 to reliably recapitulate TBI-dependent proteinopathy or APOE genotype to incorporate the risk of poor recovery post-TBI." (PMID 34210174, 2021). "APOE*4 is also associated with AD-related proteinopathies: Aβ, tau, α-synuclein, and TDP-43." (PMID 34935119, 2022). "Pathologically, APOE*ε4 has been associated with exacerbated TDP-43 proteinopathy in FTLD." (PMID 33148290, 2020). "Stepwise elimination of non-significant variables indicated 3 attributes that predicted an earlier onset age: possession of a PSEN1 mutation, possession of an APOE- ε4 genotype, and presence of TDP-43 proteinopathy." (PMID 39656832, 2025). "Our data suggest that the type of concomitant proteinopathies influences the spectrum of Aβ deposition, impacted also by sex and APOE genotypes." (PMID 37652560, 2023). "The resulting neuroinflammatory cascade, amplified by systemic inflammation and genetic factors, such as APOE ε4, establishes a self-perpetuating cycle that links proteinopathy to immune dysregulation, oxidative stress, and mitochondrial dysfunction, underscoring the complexity of AD pathogenesis." (PMID 40427569, 2025).
Sleep apnea (17 papers, 2013 to 2025). An intermittent cessation of airflow at the mouth and nose during sleep is known as sleep apnea. "This bidirectional association was seen in variants such as APOE, which in our study increased the risk for sleep apnea, while lowering the risk for sleep fragmentation or increasing sleep need." (PMID 41332830, 2025). "In summary, our results confirm that sleep apnea as a modifiable risk factor and APOE-e4 alleles as a genetic risk factor are each independently associated with abnormal levels of amyloid, and WHM volumes." (PMID 36688173, 2022). "The only significant interactions between the presence of sleep apnea and the presence of APOE-e4 alleles were relative to WMH volume in the total sample and in both WMH and Hippocampal volume in Black/African American participants." (PMID 36688173, 2022). "We further demonstrate that both sleep apnea and APOE-e4 are interactively associated with WHM with race-stratified analyses showing that this sleep apnea-APOE4 interaction on WHM occurred only in Black participants." (PMID 36688173, 2022). "Normal participants comprised fewer APOE-ɛ4 allele carriers and participants with sleep apnea than the MCI group (p<0.001)." (PMID 30802256, 2019). "In the present data, we provide the details of the cross-sectional study, from the Washington Heights-Inwood Community Aging Project (WHICAP) that examined the association between Apolipoprotein E (APOE-ε4) and snoring/sleep apnea." (PMID 26568979, 2015). "However, analyses did reveal that the interaction of APOE-e4 and the presence of sleep apnea were significantly associated with WMH and hippocampal volume in Black/African American, but not White participants." (PMID 36688173, 2022). "Multiple studies have also linked APOE ε4 to sleep disturbance: specifically, objective sleep disturbance in healthy older adults, an increased risk of insomnia and obstructive sleep apnoea/sleep-disordered breathing in both adults and children." (PMID 35354468, 2022). "Additionally, the apolipoprotein e-4 allele (APOE-e4), found in approximately 20% of the American population, and associated with a significantly increased risk for AD, has also been reportedly related to sleep disordered breathing." (PMID 36688173, 2022). "The data presented here serve to fill a critical gap in knowledge as these APOE mice are both closer in relative age and more closely model conditions akin to human sleep apnea physiology." (PMID 38748407, 2024). "Although APOE genotype has been evaluated within sleep disordered breathing across broad datasets in human subjects, the research investigating animal models of APOE under respiratory stress has been limited." (PMID 38748407, 2024). "Analysis via two-way ANOVA revealed that both sleep apnea (F1,199 = 6.058, p = 0.015) and APOE-e4 (F2,198 = 5.459, p = 0.005) independently, and their interaction (F2,198 = 3.827, p = 0.23), were significantly associated with WMH volume." (PMID 36688173, 2022). "Logistic Regression analyses were carried out in the total sample to assess the effects of sleep apnea and APOE-e4 on the likelihood of having abnormal amyloid levels." (PMID 36688173, 2022). "Biomarker and clinical marker data were derived from 1,387 participants at baseline (mean age = 69.73 ± 8.32; 58.6% female; 13.7% Black/African American), 18.4% of the sample had sleep apnea, and 37.9% were APOE-e4 carriers." (PMID 36688173, 2022). "As expected, given the results of the analyses in sleep apnea and APOE-e4 separately, there were few significant interactions between the presence of sleep apnea and APOE-e4 relative to the biological and clinical markers of AD explored in White and Black/African American participants." (PMID 36688173, 2022). "Approximately 37.9% were APOE-e4 carriers and 18.4% had sleep apnea." (PMID 36688173, 2022).
Sleep apnea (continued). "APOE ε4 was reported to be directly associated with OSA and symptomatic sleep disordered breathing, possession of this allele being associated with an approximate doubling of risk for apnoea-hypoxic index > 15 [OR 2.0 (1.2–3.5)] in adults and separately in children." (PMID 35354468, 2022). "Additionally, APOE-e4 (F1,1,268 = 12.324, p < 0.001) independently and the interaction of APOE-e4 and sleep apnea (F1,1,268 = 3.135, p = 0.044), but not sleep apnea independently were associated with performance on the MOCA." (PMID 36688173, 2022). "As a potential explanation, it has been proposed that APOE ε4 individuals might have more respiratory problems during sleep, supporting this hypothesis, several studies have found higher levels of tau pathology in sleep apnea patients." (PMID 34408639, 2021). "Patient was also negative for APOE and sleep apnea (3/5/22)." (PMID 39006824, 2024). "Both sleep apnea (p = 0.014) and APOE-e4 (p < 0.001), but not their interaction, were significant." (PMID 36688173, 2022).
hemorrhagic stroke (16 papers, 2001 to 2026). A stroke caused by a bleed on the brain. "Studies have also suggested that MTHFR, ACE, and Apolipoprotein E (ApoE) genes are risk factors for hemorrhagic stroke in European Caucasians, while factor V Leiden has protective rules." (PMID 39633841, 2024). "Apolipoprotein E polymorphism has emerged as one of the major genetic factors associated with the risk and prognosis of many neurological disorders and of hemorrhagic stroke in various populations." (PMID 29213291, 2017). "Genome-wideassociation studies have identified several single nucleotide polymorphisms (SNPs)associated with sporadic hemorrhagic strokes, including APOE(19q13), SLC25A44 (1q22), COL4A1 (13q34) andKCNK17 (6p21)." (PMID 28153846, 2017). "Our study suggested that both apoE ε3/ε4 genotype and ε4 carriers were risk factors for cerebral thrombosis in cortical artery region, whereas ε2 carrier was a risk factor for hemorrhagic stroke in the elderly." (PMID 11434425, 2001). "Similarly, ApoE ε2 carrier status was associated with hemorrhagic stroke in individuals aged 60 years old and older in a Bangladeshi study." (PMID 34276537, 2021). "Furthermore, APOE*ε2 is associated with higher chances of both ischemic and hemorrhagic stroke recurrence." (PMID 33148290, 2020). "Based on epidemiologic studies showing association of lower cholesterol levels to hemorrhagic stroke including subarachnoid hemorrhage, it may be speculated that lipid metabolism involving APOE contributes to risk of SAH or its adverse outcomes." (PMID 17672902, 2007). "However, a study has reported that the apolipoprotein E (APOE) ε2 polymorphism might contribute to variability in outcomes after hemorrhagic stroke." (PMID 25261976, 2014). "APOE*ε2 is associated with an increased risk of cerebral amyloid angiopathy (CAA) which often co-exists with AD pathology and is a major cause of hemorrhagic stroke." (PMID 33148290, 2020). "For hemorrhagic stroke, two loci (APOE and PMF1) have been identified." (PMID 27796860, 2016).
open-angle glaucoma (16 papers, 2009 to 2026). Chronic outflow obstruction of the eye's drainage canals that can lead to increased internal eye pressure and optic nerve damage. "The e4 allele of the APOE gene has been also considered in the pathophysiology of open-angle glaucoma, although the question still remains elusive." (PMID 24936186, 2014). "However, controversies persist regarding the impact of APOE single-nucleotide polymorphisms (SNPs) on open-angle glaucoma and NTG." (PMID 38637538, 2024).